CEACAM20 (CEA cell adhesion molecule 20)
Description:
Together with the tyrosine-protein kinase SYK, enhances production of the cytokine CXCL8/IL-8 via the NFKB pathway and may thus have a role in the intestinal immune response.
Synonyms: UNQ9366
Tractability: Antibody: UniProt places it where antibodies can reach, with medium confidence; UniProt predicts a signal peptide or a membrane-spanning region; its Gene Ontology location is reachable by antibodies, with medium confidence.
Gene: Protein-coding gene on chromosome 19 (44,501,677 to 44,529,788, reverse strand). Ensembl gene ENSG00000273777.
Subcellular location: Cell projection, microvillus membrane; Apical cell membrane
Gene Ontology:
Molecular function: protein tyrosine kinase binding
Biological process: regulation of immune system process; signal transduction; positive regulation of cytokine production; response to bacterium
Cellular component: cell surface; plasma membrane; apical plasma membrane; microvillus membrane
Genetic constraint (gnomAD): Loss-of-function variants: 49 observed, 58.98 expected, observed/expected ratio (o/e) 0.83, 90% interval 0.66 to 1.05. The upper end of that interval is the gene's LOEUF score, 1.05, which puts it in group 4 of 6, group 1 being the genes least tolerant of losing a copy. Missense variants: 674 observed, 748.2 expected, observed/expected ratio (o/e) 0.9, 90% interval 0.85 to 0.96. Synonymous variants: 277 observed, 289.2 expected, observed/expected ratio (o/e) 0.96, 90% interval 0.87 to 1.06.
Homologues: Orthologues: chimpanzee CEACAM20 (98% identical), macaque CEACAM20 (91% identical), dog CEACAM20 (61% identical), pig CEACAM20 (60% identical), rat Ceacam20 (54% identical), mouse Ceacam20 (53% identical), zebrafish si:ch211-264f5.6 (20% identical), zebrafish si:dkey-11o1.3 (9% identical), zebrafish si:dkey-250k15.7 (9% identical), zebrafish zgc:198329 (8% identical), zebrafish si:dkey-11o1.2 (8% identical), zebrafish si:dkey-250k15.10 (8% identical), and 3 more. Paralogues in human: CEACAM1 (21% identical), CEACAM5 (20% identical), CEACAM16 (14% identical), PSG9 (14% identical), PSG8 (14% identical), PSG4 (14% identical), PSG7 (14% identical), PSG6 (14% identical), PSG3 (13% identical), CEACAM6 (13% identical), CEACAM8 (13% identical), PSG1 (13% identical), and 12 more.
Diseases named in the same sentence as CEACAM20 in open-access papers:
CEACAM20 is named in the same sentence as 5 diseases in open-access papers, as found by Europe PMC text mining. Sharing a sentence is not in itself a finding about the gene and the disease. The quoted sentences say what the papers report.
inflammatory bowel disease (1 paper, 2021). A spectrum of small and large bowel inflammatory diseases of unknown etiology. "Interestingly, its upregulation was also observed in IBD (inflammatory bowel disease), while CEACAM20 was downregulated." (PMID 34659373, 2021).
prostate carcinoma (1 paper, 2013). A carcinoma that arises from epithelial cells of the prostate gland. "In this respect, the finding that loss of CEACAM1 and CEACAM20 is associated with loss of normal lumen structure in human high Gleason Grade prostate cancer is recapitulated in the in vitro model system." (PMID 23358633, 2013). "Since prostate cancer often involves loss of epithelial lumen formation, we hypothesized that CEACAM20 and CEACAM1 play important roles in lumen formation of normal prostate epithelium." (PMID 23358633, 2013). "Given the interest in the identification of new markers for prostate cancer, we isolated mRNA and proteins from frozen prostate tissues and found that both CEACAM20 mRNA and protein was expressed in normal prostate and prostate tumors." (PMID 23358633, 2013). "Since prostate cancer is the second leading cause of cancer deaths in men (CDC report in 2007), we began functional studies of CEACAM20 in the prostate." (PMID 23358633, 2013). "CEACAM20, a novel member of the CEACAM1 gene family with expression limited to the lumen of small intestine, testes, and prostate, is co-expressed with CEACAM1 in adult prostate tissue and down-regulated to the same extent as CEACAM1 in prostate cancer." (PMID 23358633, 2013). "We found a similar expression pattern for CEACAM20 in normal vs malignant prostate using immunohistochemistry staining (IHC), suggesting the possibility that down regulation of CEACAM1 and/or CEACAM20 is responsible for the absence of lumina in high Gleason grade prostate cancer." (PMID 23358633, 2013). "The finding that CEACAM1 and CEACAM20 staining was confined to the lumina in normal glands and the absence of staining in malignant glands lacking lumina, suggested the possibility that down-regulation of both CEACAM1 and CEACAM20 was responsible for the absence of lumina in prostate cancer." (PMID 23358633, 2013).
tumor (1 paper, 2013). "The clinical relevance of these studies suggests that both CEACAM1 and CEACAM20 can be used to further assess the degree of tumor differentiation." (PMID 23358633, 2013).
CEACAM20 also shares sentences with these, for which no sentence is quoted: colitis (2 papers); prostate tumors (1).